HIF1A (hypoxia inducible factor 1 subunit alpha)
Diseases named in the same sentence as HIF1A in open-access papers (continued):
Sharing a sentence is not in itself a finding about the gene and the disease.
tumor (continued). "The process is triggered by various stimuli received by the cancer cells from the tumour microenvironment, one of which is hypoxia-mediated HIF1-α activation, which plays a critical role in the initiation and orchestration of EMT." (PMID 34099013, 2021). "Positive HIF1α staining has been detected in some endothelial cells and in tumour infiltrating immune cells." (PMID 34433833, 2021). "Although it is known that both TGF-β and HIF-1α can regulate the glucose metabolism of tumor cells, the effect of high expression of HIF-1α induced by hypoxia on the regulation of TGF-β/Smad signaling is poorly understood." (PMID 34930376, 2021). "Paradoxically, deletion of HIF-1α in NK cells reduces tumor growth in mice despite blunted NK cell tumor killing." (PMID 33670082, 2021). "Apurinic/apyrimidinic endonuclease-1 (APEX1) is a multi-functional protein that regulates several transcription factors, including HIF-1α, that contribute to tumor growth, oxidative stress responses, and DNA damage." (PMID 33990544, 2021). "In a hypoxic microenvironment, the expression of PD-L1 on tumor cells was upregulated by HIF-1α and augments their binding with its receptor, PD-1, on T cells." (PMID 33532902, 2021). "HIF-1α is up-regulated in almost all types of tumors and is involved in initiating transcription of several genes involved in tumor growth adaptation to anoxic environment." (PMID 34660700, 2021). "Next, we investigated the effect of melatonin derivatives 1, 2, 6, and 7 on the expression of HIF‐1α, which is essential for tumor progression." (PMID 33955074, 2021). "Many strategies have been used in restraining tumor progression and chemoresistance by targeting HIF-1α." (PMID 35004677, 2021). "Although the relationship between HIF-1a expression and tumor progression has been described in head and neck cancer, there is no data on HiF1 beta and its interaction with other biomarkers of OSCC progression." (PMID 33920263, 2021). "Tocotrienol, an anti-angiogenic agent, inhibits the production of angiogenic factor by inhibiting HIF-1α, which significantly reduces tumor proliferation." (PMID 33959617, 2021). "The expression of HIF-1α and its regulated genes can be detected in relative hypoxic regions, such as 100 μm from effectual blood vessels in tumor tissues." (PMID 34671022, 2021). "HIF-1α promotes the progression and malignant characteristics via its target genes participating in the cellular survival, tumor angiogenesis, aberrant metabolism, and therapeutic resistance." (PMID 34869045, 2021). "All these data demonstrated that PESV treatment inhibited tumor formation via decreasing the expression of circ_0016760 and HIF1A and increasing miR-29b expression level in vivo." (PMID 34838012, 2021). "On the other hand, hypoxia-inducible factor 1-alpha (HIF-1α) up-regulates the expression of immune checkpoint molecules in tumor." (PMID 34149730, 2021). "Metabolic adaptation can be observed in case tumor cells survive the consequences of anti-angiogenetic or anti-HIF1α treatments." (PMID 34257622, 2021). "Using a transgenic model of MBC (MMTV-PyMT), we have shown that HIF-1α is essential for tumor growth and for the metastatic lung colonization of cells originating from the mammary gland." (PMID 35008190, 2021). "In tumorigenesis, hypoxia can stimulate the proliferation of tumor cells via a HIF-1α-dependent transcriptional mechanism." (PMID 34136065, 2021).
tumor (continued). "The paper by Zhang suggests a complex reaction in hypoxic tumour cells, where HIF-1α expression was increased, suggesting a role for this protein in regulating bystander response in hypoxic cells." (PMID 34445354, 2021). "Judging the actual importance of the HIF-1α response and of glycolysis and cellular respiration will require tumor models where hypoxia critically limits the NK cell dependent anti-tumor activity." (PMID 33782423, 2021). "Tumor hypoxia upregulates the transcription factor HIF1α that favours the recruitment of regulatory T-cells (Tregs) and increases the expression of PD-L1 in tumor cells." (PMID 33869665, 2021). "Several studies have confirmed that the expression of HIF-1α increases oxygen scarcity, which enhances the expression of other genes that indirectly benefit tumor cells in various ways." (PMID 34869321, 2021). "Differential expression of HIF-1a was also observed between tumor tissues and peri-tumor tissues, and the positive expression was mainly concentrated in the nucleus." (PMID 34815366, 2021). "Ample evidence suggested that intratumoral hypoxia and HIF1α play an essential role in the regulation of tumor immune responses." (PMID 34068008, 2021). "We identified CKB as an HIF-1α-dependent target gene necessary for tumor outgrowth and lung metastasis in the MMTV-PyMT transgenic model of MBC." (PMID 35008190, 2021). "Increased Pro and HPro production in tumor cell lines in response to hypoxia is regulated by HIF-1α." (PMID 34822413, 2021). "As for HK2, it has been shown to be required for tumor initiation and maintenance, and HIF-1α has been shown to upregulate HK2 expression, leading to pro-survival and epithelial-to-mesenchymal transition in BC." (PMID 34298771, 2021). "HIF‐1α is a pivotal transcription factor involved in many biological processes, such as tumour cell survival, angiogenesis, invasion and tumour therapy." (PMID 33943003, 2021). "MiR-143 is a tumour suppressor that is downregulated in CRC and inhibits tumour angiogenesis via the PI3K/AKT/HIF-1α/VEGF pathway." (PMID 33865381, 2021). "A recent single-cell RNA-seq study has shown that the depletion of HIF-1α in mouse NK cells elevates antitumor activity and inhibits tumor growth." (PMID 34489925, 2021). "Since the abnormally increased glycolysis of tumor cells was mainly manifested as increased pyruvate production and lactic acid production, we also tested the effect of HIF-1α on lactic acid production in IH." (PMID 34660700, 2021). "In fact, both HIF-1α and Nrf2 stress response pathways exist in a complex, interactive signalling network that stimulates tumour progression, angiogenesis, metabolic shifts and chemoresistance." (PMID 34829672, 2021). "Collectively, knockdown of lncRNA-MIR210HG impairs tumor growth in mice by inhibiting tumor angiogenesis and HIF-1α/VEGF expression." (PMID 34900667, 2021). "Pathway analysis revealed two TME-derived growth factors, IGF1 (log2 fold change = 6.55) and EGF (log2 fold change = 5.24) that are driving Hif1α signaling within the HCC tumor cells." (PMID 33995488, 2021). "Compared with other groups, the HCR-twist/HIF-1α siRNA system achieved much more effective downregulation of twist/HIF-1α tumour gene and protein expression, demonstrating the cooperatively enhanced gene-silencing abilities of twist and HIF-1α siRNAs." (PMID 34172725, 2021). "Meanwhile, we found that HIF1A, which is up-regulated in 15 tumor types served as a master TF for the HGLO phenotype in 7 of them, as tumor formation associated gene SNAPC1 was identified as its downstream target in 6 cancers." (PMID 34030708, 2021). "In short, HIF-1α activation in tumor cells is one of the mechanisms that guide its adaptation to hypoxia." (PMID 33819917, 2021).
tumor (continued). "Comparing histological sub-types, adenocarcinoma (AC) expressed lower levels of HIF-1α than squamous cell carcinoma (SqCC) (based on tumour positive cells in immunostainings)." (PMID 34298636, 2021). "Significantly fewer HIF-1α cells were positive in tumor tissues of the RT + AL-HA-Tyr, than the RT group (6.3 ± 1.4% vs. 52.0 ± 0.8%, P < 0.001), indicating that RT + AL-HA-Tyr significantly improved hypoxia." (PMID 33777779, 2021). "It is important to highlight that HIF-1α can also be subjected to negative regulation by tumour suppressors such as Von Hippel-Lindau (VHL) and (PTEN)." (PMID 34798868, 2021). "For the in vivo experiments, the data suggested that administration of Huaier obviously inhibits the tumour volume and weight, as well as the decrease of glucose metabolism level and HIF‐1α staining in tumour‐bearing tissues." (PMID 33377619, 2021). "Recently, it was observed that HIF-1α upregulation induced in tumor-infiltrating NK cells is detrimental to NK cell anti-tumor capacities." (PMID 33546248, 2021). "Among these tumor suppressor genes, the mutation of VHL can result in the overexpression of hypoxia-inducible factor-1 alpha (HIF-1α) protein, which is considered a hallmark of KIRC." (PMID 34778292, 2021). "The secretion of IL1A and IL6 in the serum of patients with higher HIF1α mRNA expression was significantly higher than the patients with lower HIF1α mRNA levels in tumor samples." (PMID 34362882, 2021). "Cellular response to hypoxia is primarily regulated by HIF1α, which in hypoxic cells stabilizes, translocates to the nucleus, and activates a number of transcriptional programs that promote cell survival, tumor growth, and metastasis." (PMID 33859337, 2021). "Hypoxia inducible factor-1α (HIF-1α) is cellular expression product for hypoxic response due to hyperactive proliferation of tumor, and many studies have proved the correlation between HIF-1α and metastasis, angiogenesis and resistance." (PMID 34329303, 2021). "The expression of HIF-1α induced by a hypoxic environment can promote GC-related angiogenesis, increase the blood supply in the tumor tissues, and thus continuously supply the rapid growth of the tumor." (PMID 34671022, 2021). "Analysis using xenograft tumor assays showed that HIF1α R282 methylation was important for its oncogene function." (PMID 34753906, 2021). "It promotes gene transcription of pro-angiogenic proteins such as HIF-1α during periods of oxygen scarcity (hypoxia) to enhance tumor growth and angiogenesis stimulation." (PMID 33836774, 2021). "The abundance of circAGFG1 and HIF-1α mRNA was markedly decreased in tumor tissues of the sh-circAGFG1 group compared with that of the sh-NC group." (PMID 34013042, 2021). "In another study, a microfluidic device was utilized to create a 3D microvascular model of breast cancer seeded under different oxygen condition to explore the role of HIF-1α in tumor extravasation." (PMID 33417986, 2021). "HIF-1α is known to induce low oxygen levels found in the tumor microenvironment, mainly in solid tumors." (PMID 33544704, 2021). "Expectedly, MAP17-dependent glycolysis and tumor growth were effectively blocked by MK-2206 or HIF1α knockdown." (PMID 33832535, 2021). "Hypoxia promotes glycolysis and increases glucose uptake by tumor cells through HIF1α upregulation and stabilization." (PMID 33923299, 2021). "We showed that tumors expressing a deleted form of HIF-1α displayed increased levels of NK and CD8+ effector T cells in the tumor microenvironment, which was associated with high levels of CCL2 and CCL5 chemokines." (PMID 34155342, 2021). "To test if HIF1A is critical for tumor growth in primary GBM cells, we performed similar experiments in xenograft mice using Glio-1 and Glio-2 cells." (PMID 34470658, 2021). "A decrease in HIF-1α serum level was observed in concurrence with tumour reduction and potentially predicted treatment response (p < 0.001)." (PMID 34298636, 2021).
tumor (continued). "The effectiveness of TSA is reduced by overexpression of HIF-1α or hypoxic conditions, which leads to drug resistance in tumor cells." (PMID 34552922, 2021). "Some studies showed HIF1α acting as an oncogenic role, while others showed HIF1α acting as a tumor suppressor role." (PMID 34384473, 2021). "In most cases, tumor growth depends on VEGF release; in parallel, hypoxia in the tumor microenvironment leads to intracellular stabilization of HIF-1α." (PMID 34209857, 2021). "Strikingly, also the recruitment of NK cells into the tumor nests can be inhibited by hypoxia via HIF-1α." (PMID 34696251, 2021). "HIF-1α plays a pivotal role in promoting radiotherapy- and chemotherapy-resistance of malignant tumor cells 23-30, tumor angiogenesis 31-32, cancer cell metabolism 33-35, cell proliferation 36, 37, and cell migration and invasion 38-40." (PMID 34093799, 2021). "In the context of hypoxia, HIF1α directs glucose away from mitochondria, leaving Treg cells dependent on fatty acids for mitochondrial metabolism within the hypoxic tumor." (PMID 33748292, 2021). "Our findings are supported by the results from a recent study that activation of cyclin-dependent kinase 1 (CDK1) phosphorylated HIF-1α protein and led to tumor growth." (PMID 33920906, 2021). "COMMD1 has been demonstrated to inhibit HIF-1 transcription activity by competing with HIF-1β for binding to HIF-1α in human tumor cells." (PMID 33716719, 2021). "It is important to note that HIF1A and c-Myc are both known to regulate the expression of tumor-specific isoforms of glycolytic proteins such as GLUT1, HK2, PKM, and LDHA, thereby diminishing the Warburg effect in cancer cells." (PMID 34692483, 2021). "Topotecan is proven to decrease HIF-1α accumulation in the combination of bevacizumab to inhibit tumor growth in U251 hypoxia response element xenografts." (PMID 34504845, 2021). "Studies have established that EMT-TFs, under the action of hypoxia-inducible factor −1α (HIF1A), resisted the anti-tumor effect of CD8 + T cells." (PMID 34180352, 2021). "HIF-1α, which is induced by growth factors, hypoxia, and oncogenes, plays a critical role in tumor metabolic reprogramming, growth, and angiogenesis." (PMID 34257808, 2021). "The efficacy of TACE can be affected by tumor angiogenesis of the residual disease, in which HIF-1α and VEGF play key roles in response to hypoxia." (PMID 33685316, 2021). "PD-L1 is a target of HIF-1α, and upregulation of PD-L1 on tumor cells in the hypoxic tumor core interacts with PD-1 on activated T-cells, leading to T-cell anergy and exhaustion or even apoptosis." (PMID 34359588, 2021). "Tumors can further use a series of signaling pathways that are activated during hypoxia, which are represented by hypoxia-inducible factor 1-alpha (HIF1α), to promote tumor growth." (PMID 33869223, 2021). "According to this literature review, the mechanisms used by sestrin 2 to inhibit tumor growth are mainly associated with mTOR, iNOS, XIAP, and HIF-1α signaling pathways." (PMID 34784907, 2021). "On a molecular level, hypoxia induces the transcription of Hypoxia-inducible factor-1α (HIF-1α), a key molecule that promotes an aggressive tumor phenotype, by stimulating angiogenesis, tissue invasion or metastasis." (PMID 34833391, 2021). "HIF-1α is expressed in all immune cells, whereas the expression pattern of HIF-2α is limited to several sub-types such as T cells, tumor-associated macrophages, and neutrophils." (PMID 34571989, 2021).
tumor (continued). "Inhibiting tumor angiogenesis by preventing the HIF-1α/VEGF/VEGFR-2 signaling pathway is believed to be a potential solid tumor-targeted therapy." (PMID 33637686, 2021). "CXCL12 gene expression in tumor cells is controlled by HIF-1α in direct proportion to reduced oxygen level in ischemic endothelial cells." (PMID 34200145, 2021). "CD147 expression has also been demonstrated to be regulated by HIF-1α, promoting glycolysis and inhibiting tumor cell apoptosis." (PMID 33718271, 2021). "HIF-1α has been identified as one of the key regulators in tumor progression, cell proliferation, invasion and angiogenesis." (PMID 33919449, 2021). "The anti-tumor effect exerted by idelalisib through HIF-1α inhibition in cancer cells, as well as in SC, would certainly need a validation in a larger cohort of CLL patients." (PMID 34207596, 2021). "Consistent with our previous findings, HACE1 protein levels were reduced in all tumor cases tested (n = 3) compared to the patient-matched normal kidney, while HIF1α levels were correspondingly increased." (PMID 33603169, 2021). "In vivo, during tumour formation, the expression of Ki‐67 and proliferating cell nuclear antigen (PCNA) in the tumour tissue with HIF‐1α KO fibroblasts was significantly lower than that of normal fibroblasts." (PMID 33943003, 2021). "Hypoxic TAMs release macrophage migratory inhibitory factor (MIF), which stabilizes HIF-1α protein, eventually promoting the degradation of basement membranes in tumors and providing an easy escape for tumor cells." (PMID 34131104, 2021). "Hypoxia inducible factor 1α (HIF-1α) plays a key role in tumor angiogenesis and regulates the expression level of VEGF." (PMID 34013046, 2021). "In hypoxic conditions, HIF-1α induces tumor angiogenesis, proliferation, metastasis and inhibits apoptosis of cancer cells." (PMID 35095479, 2021). "Our results demonstrated that the higher protein level of USP14 was not only positively correlated with that of the HIF1-α, but also closely related to the clinical stage, tumor differentiation, and patient prognosis of HCC." (PMID 34420039, 2021). "Accordingly, expression of HIF1α in tumor tissues increased with time after PDT, indicating that PDT disrupted tumor vessels and induced hemorrhage and thrombosis, which further intensified hypoxia in tumor grafts." (PMID 33754061, 2021). "For EGFR sensitive mutation group containing 233 cases, the P value and R2 value of correlation analysis between tumor diameter and HIF-1α level were 0.056 and 0.469, so we can’t absolutely deny the correlation." (PMID 33441708, 2021). "On the other hand, the densified tumor stroma reduces the oxygen diffusion in tumor tissues and promotes the expression of hypoxia-inducible factor 1α (HIF1α), which induces immune checkpoint marker expression and immunosuppressive cytokines release." (PMID 34098945, 2021). "With the ultrasound, oxygen microbubbles improved the morphology and function of the tumor vasculature via increased tumor oxygenation and inhibited HIF-1α and VEGF expression." (PMID 33230600, 2021). "As a result, TAK‐779 neutralized the enhancement effect of HIF‐1α expression fibroblasts on the proliferation and clone formation of tumour cells." (PMID 33943003, 2021). "HIF-1α activation in tumor cells is one of the key masters orchestrating their adaptation mechanisms to the hypoxia environment." (PMID 33664256, 2021). "Decreased WWOX expression in GDM compared to normal pregnancy, and in particular reduction of WWOX/HIF1A ratio, indicate that WWOX modulates HIF1α activity in normal tissues as described in the tumor." (PMID 33520443, 2021). "Reduced oxygen levels in tumor tissues result in the stabilization and accumulation of HIF-1α, which plays a key role in the adaptive response of cancer cells to hypoxia by modulating various cellular functions." (PMID 34381712, 2021).